NOTCH1 (notch receptor 1)
Diseases named in the same sentence as NOTCH1 in open-access papers (continued):
Sharing a sentence is not in itself a finding about the gene and the disease.
T-cell acute lymphoblastic leukemia (continued). "Chromosomal rearrangements and mutations of the NOTCH1 gene were initially described in T-cell acute lymphoblastic leukemia (T-ALL), which displayed aberrant activation of NOTCH1 signaling in over 60% of the cases." (PMID 29998084, 2018). "Two out of 36 frozen tumor samples harbored frame shift mutations within the PEST domain of NOTCH1, which are well-described activating mutations of NOTCH1 in T-cell acute lymphoblastic leukemia." (PMID 28636652, 2017). "Immature pre-T cells are particularly susceptible to transformation by excessive Notch signaling, as more than 50% of T cell acute lymphoblastic leukemias (T-ALL) derived from these cells have mutations causing ligand-independent NOTCH1 activation." (PMID 29023469, 2017). "Human T-cell acute lymphoblastic leukemia (T-ALL) is generally associated with NOTCH1 gene mutations that trigger an aberrant and constitutively active NOTCH1 signaling." (PMID 27177333, 2016). "Oncogenic gain-of-function mutations in NOTCH1 commonly occur in human T-cell acute lymphocytic leukemia (T-ALL) and B-cell chronic lymphocytic leukemia." (PMID 27093186, 2016). "Human T cell acute lymphoblastic leukemia (T-ALL) is generally characterized by mutations that activate the NOTCH1 signaling." (PMID 25927065, 2015). "It must be noted that specific T-cell acute lymphoblastic leukemia (T-ALL) cells harboring Notch1 activating mutations were refractory to γ-secretase treatment." (PMID 24959218, 2014). "In human T-cell acute lymphoblastic leukaemia and lymphoma (T-ALLs) aberrant Notch activity is caused by mutations of NOTCH1 and FBXW7 in more than 50% of patients." (PMID 24357640, 2014). "Notch1 is a transmembrane receptor that is frequently mutated in human T-cell acute lymphoblastic leukemia (T-ALL)." (PMID 24068942, 2013). "Activating mutations in NOTCH1 occur commonly in T cell acute lymphoblastic leukemia (T-ALL) and have been implicated in therapeutic resistance." (PMID 22768113, 2012). "The Notch signaling pathway is crucial in T-cell development, Notch1 mutations are frequently present in T-cell acute lymphoblastic leukemia (T-ALL)." (PMID 22480166, 2012). "Remarkably, 40% to 50% of human T-cell acute lymphocytic leukemias harbor mutations within the NRR of Notch1." (PMID 21829530, 2011). "The homeobox gene TLX1 (for T-cell leukemia homeobox 1, previously known as HOX11) is inappropriately expressed in a major subgroup of T cell acute lymphoblastic leukemia (T-ALL) where it is strongly associated with activating NOTCH1 mutations." (PMID 20618946, 2010). "Activating mutations within the extracellular and PEST domains of NOTCH1 have been observed in human T-cell acute lymphoblastic leukaemia, in which NOTCH1 plays an important role." (PMID 19285540, 2009). "IGF2BP2 can directly bind to NOTCH1 and stabilize NOTCH1 mRNA expression in an m6A dependent manner, and the widespread expression of NOTCH1 may be closely linked to the presence of T-cell acute lymphoblastic leukemia (T-ALL)." (PMID 38711100, 2024). "These NOTCH1 variants appear to have similar function to those observed in chronic lymphocytic leukemia and mantle cell lymphoma, but are distinct from the membrane-proximal NOTCH1 mutations in T-cell acute lymphoblastic leukemia." (PMID 35060000, 2022). "Mutations in human NOTCH1 can cause aortic valve disease and T-cell acute lymphoblastic leukemia." (PMID 26999814, 2016). "T-cell acute lymphoblastic leukemia (T-ALL) is a malignant neoplasm associated with mutations in genes NOTCH1 and FBXW7." (PMID 37681873, 2023). "Only a few genes, such as HES4, HEY1, MYC, NOTCH3, NRARP, and TFRC, are similarly regulated in mutationally activated NOTCH1-driven cancers, such as T-cell acute lymphoblastic leukemia (T-ALL), mantle cell lymphoma (MCL), and breast cancer." (PMID 33003595, 2020).
T-cell acute lymphoblastic leukemia (continued). "Deletion of the genes Zfp36L1 and Zfp36L2, which encode RNA-binding proteins, was shown to cause T-cell acute lymphoblastic leukemia (T-ALL) in mice due to impaired Notch1 mRNA degradation." (PMID 30144809, 2018). "For example, notch receptor 1 (NOTCH1 [MIM: 190198]) displays two distinct mutational concentration areas in the gene regions encoding the heterodimerization and the PEST domain in T cell acute lymphoblastic leukemia." (PMID 40359938, 2025). "SIRT1 enhances NOTCH1-induced T-cell acute lymphoblastic leukemia (T-ALL) development and mediates resistance to NOTCH1 inhibition in a deacetylase-dependent mechanism." (PMID 39479446, 2024). "T-cell ALL (T-ALL) is an aggressive hematological neoplasm deriving from the malignant transformation of T-cell progenitors characterized by frequent NOTCH1 pathway activation." (PMID 38928249, 2024). "A previous study highlighted KDM6B’s crucial role in supporting NOTCH1-driven T cell acute lymphoblastic leukemia." (PMID 38566223, 2024). "Previous work has shown that mice with double KO of Zfp36l1 and Zfp36l2 in T cells during thymopoiesis develop T cell acute lymphoblastic leukemia because of changes in Notch-1 signaling." (PMID 37903626, 2024). "VAV1 silences NOTCH1 signaling and suppresses T cell acute lymphoblastic leukemia by promoting the degradation of the intracellular domain of NOTCH1 (ICN1) through ubiquitination and proteasomal degradation." (PMID 39200159, 2024). "Notch1 has been widely described as one of the driver genes in T-cell acute lymphoblastic leukemia/lymphoma (T-ALL) (88, –, 90), while Ppp1r16b can promote aggressive lymphomas in mice." (PMID 35852337, 2022). "Several pairs of co-occurring mutations were found: NRAS with SETD, NRAS with PTPN11 in B-cell ALL (p = 0.024 and p = 0.020, respectively), and NOTCH1 with FBXW7 in T-cell ALL (p < 0.001)." (PMID 36362526, 2022). "Combining cDNA microarray and ChIP-seq analysis, we identify Rag1 and Rag2 as novel Notch1 transcriptional targets in acute T-cell lymphoblastic leukemia (T-ALL) cells." (PMID 34322489, 2021). "ASB2, regulated by Notch1, promotes NF-κB activation in T-cell acute lymphoblastic leukemia, and based on a genetic screen, it is a putative DLBCL essential gene." (PMID 34763718, 2021). "ADAM10-mediated Notch1 cleavage and shedding in T-cells controls T-cell development, and also contributes to oncogenic Notch signaling by shedding Notch1 mutants in T-cell acute lymphoblastic leukemia (T-ALL)." (PMID 33413403, 2021). "It is known that in T-cell acute lymphoblastic leukemia (T-ALL), where more than 50% of patients have activating NOTCH1 mutations, GSIs efficiently inhibit Notch1 oncogenic protein." (PMID 34202439, 2021). "Disruption or abnormal expression of NOTCH receptors (NOTCH 1 to 4), particularly NOTCH 1, affects hematopoietic cell homeostasis and is common in hematological malignancies including T-cell Acute Lymphocytic Leukemia (T-ALL)." (PMID 33770102, 2021). "Initially, the oncogenic role of Notch signaling was documented in T cell Acute Lymphoblastic Leukemia (T-ALL), where the activating mutations in NOTCH1 were suggested to be a major mediator for the development of malignancy." (PMID 33968932, 2021). "Notch1 is a crucial oncogenic driver in T-cell acute lymphoblastic leukemia (T-ALL), making it an attractive therapeutic target." (PMID 33947863, 2021). "NOTCH1 is a driver of T-cell acute lymphoblastic leukemia that can be inhibited by γ-secretase inhibitors (GSIs), but their clinical efficacy is limited." (PMID 33947863, 2021). "Loss of Fbw7 in hematopoietic cells or T cells of conditional knockout mice is sufficient to cause T-cell acute lymphoblastic leukaemia (T-ALL) or thymic lymphoma, in which increased levels of Notch1 and c-Myc are seen." (PMID 32873855, 2020).
T-cell acute lymphoblastic leukemia (continued). "In T-cell acute lymphoblastic leukemia, the intracellular domains of NOTCH1 and NOTCH3 are effectively interchangeable in their ability to drive the expression of downstream target genes that support the aberrant cell growth." (PMID 32908186, 2020). "In other cellular contexts, it has also been observed that NOTCH1 and NOTCH3 signaling is very similar, for example in acute T-cell lymphoblastic leukemia, in which the activation of both NOTCH1 and NOTCH3 has the ability to induce T-ALL64." (PMID 32908186, 2020). "In the mammalian blood system, for example, Notch1 mutations that remove an NICD degron sequence have been associated with increased NICD levels and the development of T-cell Acute Lymphoblastic Leukemia (T-ALL) in mice and humans." (PMID 32297857, 2020). "One of the 37 unique genes selected by IGIS+ is M21624 (TCRD T-cell receptor, delta), which is a crucial biomarker for being a direct target of activated NOTCH1 and being upregulated in T-cell ALL." (PMID 30768654, 2019). "The oncogenic role of NOTCH1 has been verified in a number of hematological diseases, including T-cell acute lymphoblastic leukemia, multiple myeloma, Hodgkin and anaplastic large cell lymphoma." (PMID 30777096, 2019). "NOTCH1 is required for normal T cell development and is a key oncogenic driver in human T cell acute lymphoblastic leukemia (T-ALL)." (PMID 31311566, 2019). "It was reported previously that ZMIZ1, in collaboration with NOTCH1, induce T-cell acute lymphoblastic leukemia (T-ALL) in mice." (PMID 31221986, 2019). "Although studies demonstrated that Notch was an oncogene in many tumors, and Notch1 was exclusively oncogenic in hematological malignancies such as T cell acute lymphoblastic leukemia, recent studies suggest that Notch was a tumor suppressor in AML." (PMID 31849658, 2019). "Utx, a di- and trimethyl H3K27 demethylase, is required for normal hematopoiesis; meanwhile, Utx serves as a tumor suppressor in NOTCH1-induced T cell acute lymphoblastic leukemia (T-ALL)." (PMID 29482581, 2018). "T cell acute lymphoblastic leukemia (T-ALL) is a highly aggressive disease caused by malignant transformation of early T cell progenitors, characterized by mutation of NOTCH1." (PMID 30103821, 2018). "Functional similarities and differences determined by NOTCH1 in influencing the biological behavior of T-cell acute lymphoblastic leukemia (T-ALL) and B-cell chronic lymphocytic leukemia (B-CLL) cells." (PMID 29666622, 2018). "The NOTCH1 signaling pathway is crucial for T-cell development, and NOTCH1 and/or FBXW7 mutations are frequently detected in T-cell acute lymphoblastic leukemia (T-ALL)." (PMID 29029518, 2017). "Approximately 60% of human T-cell acute lymphoblastic leukemia/lymphoma cases present NOTCH1 activation." (PMID 28968975, 2017). "Activated forms of NOTCH1 mutations, which are under the control of the TCRB locus, have been suggested to be the essential feature in T-cell acute lymphoblastic leukemia (T-ALL) pathogenesis." (PMID 29088303, 2017). "PTEN gene inactivation by mutation or deletion is common in pediatric T-cell acute lymphoblastic leukemia (T-ALL), but the impact on outcome is unclear, particularly in patients with NOTCH1/FBXW7 mutations." (PMID 26220040, 2016). "The first reported Notch1 alteration was the identification of a chromosome translocation by fusing T-cell receptor-β to ICN1 in T-cell acute lymphoblastic leukemia (T-ALL) resulting in constitutive active Notch1." (PMID 28036048, 2016). "It is possible that incorporation of NMHC in NRR mimics the function of activating mutations identified in acute T-cell lymphoblastic leukemia (T-ALL), facilitating its proteolytic cleavage and the following release of active intracellular NOTCH1." (PMID 27211848, 2016).
T-cell acute lymphoblastic leukemia (continued). "Treatment resistance in T cell acute lymphoblastic leukemia (T-ALL) is associated with PTEN deletions which result in the activation of the PI3K-Akt pathway, and Notch1-mediated c-Myc overexpression." (PMID 26405162, 2015). "Of note, constitutively active Notch1 downregulates Bim expression in other cell types (e.g., T cell acute lymphoblastic leukemia) through induction of c-Myc and repression of PTEN that leads to the activation of the PI3K/Akt/mTOR pathway." (PMID 26405162, 2015). "MiR-19 can promote leukemogenesis in Notch1-induced T-cell acute lymphoblastic leukemia (T-ALL) in vivo." (PMID 24499489, 2014). "Notch1 is a potent regulator known to play an oncogenic role in many malignancies including T-cell acute lymphoblastic leukemia (T-ALL)." (PMID 23289374, 2013). "Notch1 signaling appears to be the central oncogenic trigger in T cell acute lymphoblastic leukemia (T-ALL), in which the majority of human malignancies have acquired mutations that lead to constitutive activation of Notch1 signaling." (PMID 24252593, 2013). "al. demonstrated that calcium channels are required for the maturation of oncogenic Notch1 in T cell acute lymphoblastic leukemia." (PMID 24260356, 2013). "Here we show that deletion of mir-181a-1/b-1 expression inhibits the development of Notch1 oncogene-induced T cell acute lymphoblastic leukemia (T-ALL)." (PMID 22916024, 2012). "In the human equivalent of these T-cell lymphomas, T-cell acute lymphoblastic leukemias (T-ALL), several genetic abnormalities have been described including Notch1 mutations in a large proportion of all human T-ALL." (PMID 23185135, 2012). "NOTCH1 oncogenic potential was first reported in T cell acute lymphoblastic leukemia in the 90s." (PMID 40789681, 2025). "Mutations in the Notch1 gene are associated with diseases such as aortic valve disease, type 1 (AOVD1), Adams–Oliver syndrome type 5 (AOS5), T-cell acute lymphoblastic leukemia (T-ALL), chronic lymphocytic leukemia, and squamous cell carcinoma of the head and neck." (PMID 38790158, 2024). "It is crucial to highlight that in T cell acute lymphoblastic leukemia (T-ALL), the Notch1 activating mutations typically occurs later in a sequence of genomic damages, suggesting that Notch1-based therapies may impede the efficacy targeted Notch1 therapy." (PMID 39092224, 2024). "NOTCH1 PEST domain mutations are often seen in hematopoietic malignancies, including T-cell acute lymphoblastic leukemia (T-ALL), chronic lymphocytic leukemia (CLL), splenic marginal zone lymphoma (SMZL), mantle cell lymphoma (MCL), and diffuse large B-cell lymphoma (DLBCL)." (PMID 38255842, 2024). "Thus, we have shown that the elimination of endogenous R-Ras2 leads the abrogation of Her2-driven mammary tumorigenesis as well as of Notch1-driven T cell acute lymphoblastic leukemia." (PMID 36476833, 2023). "However, the first identified genetic alteration involving the NOTCH1 gene was detected only in less than 1% of T-cell acute lymphoblastic leukemia (T-ALL) patients." (PMID 36674902, 2023). "Indeed, ZFP36L1 and ZFP36L2 suppressed NOTCH1 expression in T cell acute lymphoblastic leukemia by interacting with the 3′ UTR of NOTCH1." (PMID 37853162, 2023). "Moreover, a novel nucleotide biosynthesis regulatory role for UBR7 has been identified in NOTCH1-driven T cell acute lymphoblastic leukemia." (PMID 36419136, 2022). "Notch1 is frequently activated promoting T-cell acute lymphoblastic leukaemia (T-ALL)." (PMID 35589701, 2022). "Activating NOTCH1 mutations is one of the most frequent gene aberration found in human T-cell acute leukemia/lymphoma and the majority of these mutations are located in the PEST or heterodimerization domain similar to the Notch1 mutations detected in lymphomas from PPM1D-transgenic mice." (PMID 34771656, 2021). "Seven patients, all with a diagnosis of T-cell ALL/LBL, had NOTCH1 mutations." (PMID 35008312, 2021).
T-cell acute lymphoblastic leukemia (continued). "NOTCH1 lesions commonly occur in more than 50% of T cell acute lymphoblastic leukaemia patients." (PMID 31959790, 2020). "One of the clearest associations between Notch activity and cancer has been provided by studies of T-cell acute lymphoblastic leukemia (T-ALL), for which mutations in NOTCH1 and regulators of Notch1 activity are common drivers by bypassing important regulatory mechanisms." (PMID 31519743, 2019). "FBXW7 mutation has been demonstrated to associate with NOTCH1 activation in T-cell acute lymphoblastic leukemia; however, not until NOTCH1’s implication in HNSCC tumorigenesis was FBXW7 linked to this disease." (PMID 30647454, 2019). "For example, Notch 1 induced LUNAR1 could drive tumor proliferation by upregulating insulin-like growth factor receptor 1 in T cell acute lymphoblastic leukemia." (PMID 30560474, 2019). "However, in accordance with previous studies, mutations in NOTCH1 tended to cluster in the proline-glutamic acid-serine-threonine (PEST) domain, similar to the activating mutations in T-cell acute lymphoblastic leukaemia." (PMID 29731974, 2018). "Oncogenic Notch1 is known to activate the NF-κB pathway in T cell acute lymphoblastic leukemia (T-ALL) and to up-regulate the transcription of Asb2α, a specificity factor for an E3 ubiquitin ligase complex that plays an important role in hematopoietic differentiation." (PMID 30116272, 2018). "NOTCH1 acts as an oncoprotein in T-cell acute lymphoblastic leukemia/lymphoma." (PMID 28968975, 2017). "Furthermore, it has been reported that PHF8 is key regulator of oncogenic functions of NOTCH1 signaling in T cell acute lymphoblastic leukemia (T-ALL), which is also dependent on its KDM activity." (PMID 24146981, 2013). "For instance, in T cell acute lymphoblastic leukemia (T-ALL), the duplication of the 8q24 region leads to the amplification of a long-range acting enhancer controlled by notch receptor 1 (NOTCH1)." (PMID 40032852, 2025). "IGF2BP2 is highly expressed in T-cell acute lymphoblastic leukemia (T-ALL), and directly binds to the T-ALL oncogene NOTCH1 in an m6A-dependent manner, thereby stabilizing its mRNA and promoting tumorigenesis." (PMID 40823087, 2025). "In T-cell acute lymphoblastic leukemia (T-ALL), more than 50% of cases display autoactivation of Notch1 signaling, leading to oncogenic transformation." (PMID 39258755, 2024). "A recent study on T-cell acute lymphoblastic leukemia (T-ALL) reported that GATA3-driven nucleosome eviction dynamically modulates NOTCH1-MYC enhancer activity and is strictly required for NOTCH1-induced T-ALL initiation and maintenance." (PMID 33918793, 2021). "In some malignancies such as acute T-cell lymphoblastic leukemia, activation of the PI3K/AKT pathway downstream of NOTCH1 signaling promotes cell proliferation at multiple levels and has an important role in T-cell transformation." (PMID 32886682, 2020). "An interconnection was reported between NOTCH1 activation and calcineurin-NFAT pathways in keratinocyte differentiation control and in T-cell acute leukemia malignancy and recidivism." (PMID 31500188, 2019). "Notch1 mutations causing Notch signaling continuously activated have been found in nearly 60% of T cell acute lymphoblastic leukemia (T-ALL) patients, making Notch1 the most prominent oncogene specifically involved in the pathogenesis of T-ALL." (PMID 24252593, 2013). "Gamma-secretase inhibition (GSI), which has been used to block oncogenic NOTCH1 signaling in T cell acute lymphoblastic leukemia, did not alter the modest upregulation of cell-surface MHC class I with short-term TAS1440 treatment." (PMID 40627448, 2025). "In addition, these mice developed T cell acute lymphoblastic leukemia (T-ALL) as a result of the impaired induction of the transcription factor TCF1 and prolonged oncogenic Notch1 signaling." (PMID 36674959, 2023).